INS (insulin)
Diseases named in the same sentence as INS in open-access papers (continued):
Sharing a sentence is not in itself a finding about the gene and the disease.
Obesity (continued). "MetS is a tremendous and increasing global health concern known as disruptions of insulin, glucose, and lipid metabolism, obesity, and hypertension." (PMID 36474567, 2022). "Insulin is an anabolic hormone, and resistance to the action of insulin in skeletal muscle is a typical consequence of obesity." (PMID 35350688, 2022). "Objective(s): One of the adipokines that have insulin-sensitizing properties is adipolin, whose reduced levels have been reported in obesity, oxidative stress, and inflammation." (PMID 36136851, 2022). "On the other hand, other authors reported that insulin resistance is higher in people with obesity than in people who are lean, even when both groups are matched by basal glycemia and hepatic and muscle insulin sensitivity." (PMID 35327570, 2022). "HFD led to obesity in mice with obvious glucose and lipid metabolism disorder, the higher insulin levels in both plasma and cerebrospinal fluid, and aberrant insulin signaling pathway in the whole brain." (PMID 36466168, 2022). "For example, in contrast to men with obesity, lean individuals report a reduction in wanting of sweet foods after IN insulin." (PMID 35397638, 2022). "It has been shown that complex interactions between the insulin and sympathoadrenal systems can lead to the development of obesity and MetS." (PMID 36005598, 2022). "Reduced muscle perfusion during a hyperinsulinemic clamp is often observed in people with obesity, and is due to both capillary rarefaction and impaired insulin-mediated vasodilation." (PMID 35054781, 2022). "Apart from its vital role in CAL homeostasis, VD–CAL is involved in modulating inflammatory, insulin, hormone, and cell functions in obesity." (PMID 35956362, 2022). "Here, we consider the evidence for the metabolic effects of resveratrol in ex vivo adipose tissue cultures, animal- and human-based studies of obesity, and finally, on insulin sensitivity and glycemic control." (PMID 35889827, 2022). "In fact, there are various mechanisms/pathways affecting fat accumulation in obesity, such as signaling pathways, chronic inflammation, insulin resistance, mitochondrial dysfunction, circadian rhythm disturbance, and so on." (PMID 35216415, 2022). "The reproductive cycle in the experimental animal has been found to improve when insulin signaling is disrupted in case of obesity induced by diet." (PMID 36320802, 2022). "Despite almost 100% of adolescents using intensive insulin therapy by 2016, rates of overweight and obesity were unchanged from 2004–2016 (39% vs. 29% in the 10–13 year group and 40% vs. 40% in the 14–17 year group)." (PMID 35715954, 2022). "Recently, several miRNAs have emerged as key agents involved in pathways related to obesity such as adipokine expression, glucose and lipid metabolism, insulin signaling, oxidative stress, and inflammation." (PMID 36142173, 2022). "Pediatric patients with overweight or obesity present hyperinsulinemia and have approximately 40% less insulin-stimulated glucose compared with children with normal-weight." (PMID 36364954, 2022). "As systemic GDF11 treatment can improve glucose homeostasis and insulin sensitivity in rodent obesity models, we tested internalization/uptake of 2‐deoxy glucose in mature 3T3‐L1 adipocytes after GDF11 treatment." (PMID 35920128, 2022). "Heligmosomoides polygyrus (H. polygyrus) infection improved insulin sensitivity and reduced fat accumulation in the liver and obesity-related inflammation in HFD mice." (PMID 36263053, 2022). "In a study in mice with an obesity-inducing diet, Yerba extract supplementation was shown to alleviate hyperglycemia and improve insulin sensitivity and plasma lipids." (PMID 35684317, 2022). "Currently available data suggest that impaired insulin secretion is primarily due to genetic factors and aging, whereas decreased insulin sensitivity is primarily due to obesity and low muscle mass." (PMID 36118835, 2022).
Obesity (continued). "In male mice fed a HFD, A. muciniphila supplementation attenuated obesity and inflammation and improved insulin signaling." (PMID 36387852, 2022). "Here, we provide an overview of the factors that regulate insulin removal from plasma and discuss the interrelationships among plasma insulin clearance, excess adiposity, insulin sensitivity, and T2D in people with obesity." (PMID 35054781, 2022). "In cases of diet-induced obesity, insulin resistance in the hippocampus—a significant brain structure in the pathophysiology of Alzheimer’s dementia (AD), which happens to densely express insulin receptors—has a negative impact on learning and memory." (PMID 36204553, 2022). "Vanadium-mediated insulin mimetic and anti-obesity action following AMPK action has also been reported using groundwater enriched with vanadium." (PMID 35159385, 2022). "The combination of a single-dose FMT and daily low-fermentable fiber intervention for 6 weeks improved insulin sensitivity in patients suffering from severe obesity and metabolic syndrome." (PMID 35185934, 2022). "Among the differentially expressed miRNAs is also miR-31-5p, which we identified in an obesity locus on chromosome 4and to affect expression of genes relevant for glucose transport and insulin signaling." (PMID 35216219, 2022). "The beneficial exercise effect on insulin sensitivity occurs after several weeks or even after a single bout of exercise in adults with obesity." (PMID 35677551, 2022). "The AKT signaling plays an essential role in glucose homeostasis mediated by insulin, and obesity-mediated glucose metabolism reduces insulin-AKT phosphorylation." (PMID 36348465, 2022). "Most Importantly, blocker that blocks parvalbumin and CSF1R interaction not only rescued M2 macrophage activation, insulin sensitivity and thermogenesis but also ameliorated obesity in mice." (PMID 35676256, 2022). "In this context, an appealing strategy to combat obesity and restore insulin sensitivity consists in increasing lipid oxidation through a controlled reduction of cellular energetic efficiency based on mitochondrial uncoupling." (PMID 36358339, 2022). "The carbohydrate-insulin model of obesity supports observations of these foods triggering abnormal blood sugar and insulin spikes subsequently leading to changes in metabolic and neurobiological signaling." (PMID 36245868, 2022). "In this design, we reported that a pMR diet produced a significant improvement in adiposity parameters, blood pressure, lipid profile, fasting glucose and fasting insulin levels, and biochemical liver parameters in subjects with obesity and FLI ≥ 60 units." (PMID 36558510, 2022). "Previous evidence suggested that the suppressor of cytokine signaling 3 (SOCS3) played an essential role in the regulation of energy metabolism homeostasis, which inhibited the activity of insulin and leptin (characteristic feature in human obesity)." (PMID 36145200, 2022). "Taken together, these observations suggest that LRG1 overexpression prevents obesity-related dysregulation of glucose homeostasis by insulin sensitization." (PMID 36346018, 2022). "Animal studies have identified major effects of tirzepatide on insulin sensitivity in mice with diet-induced obesity." (PMID 36050763, 2022). "Clearly genetic makeup can impact the relationship between obesity and glucoregulation, but less is known about the relative importance of diet composition and total fat mass in the regulation of insulin action at the whole body and tissue level." (PMID 36394259, 2022). "The current study results demonstrated that the obese group rats showed significantly increased insulin levels along with obesity, as indicated by the significant increase in cholesterol and triglycerides levels." (PMID 35972578, 2022). "Egg-derived peptides play important roles in insulin secretion and sensitivity, oxidative stress, and inflammation, suggesting their possible involvement in obesity management." (PMID 36232527, 2022).
Obesity (continued). "When the energy input rate exceeds the consumption rate for a long time, metabolic markers of obesity, such as insulin resistance and adipose tissue, develop." (PMID 36249777, 2022). "There is also growing evidence that peripheral CB1-R plays critical roles in obesity-induced pro-inflammatory responses, particularly in insulin-target tissues." (PMID 35456900, 2022). "In this study, we validated the anti-diabetic and anti-obesity effects of EG in 3T3-L1 fat cells, which are widely used for in vitro studies of insulin tolerance pathways and obesity." (PMID 35563411, 2022). "1- and 3-year remission were associated with preoperative age, duration of T2DM, FBS and HbA1c, BMI, insulin therapy, and a family history of obesity (p < 0.05)." (PMID 36289529, 2022). "Based on this result, we concluded that obesity and T2DM are associated with a decrease in adiponectin, which reduces insulin sensitivity." (PMID 36355818, 2022). "For obesity, the energy generation, while for T2D, the involvement of NO synthesis and its relation to insulin signaling and inflammation, were characteristic." (PMID 35562924, 2022). "Decreased insulin sensitivity towards blood glucose leads to over-storage in the body tissues, which further promotes obesity in women of reproductive age." (PMID 36078079, 2022). "It is therefore evident that the conclusions drawn from obesity GWAS association studies on NMB, as well as on insulin release, should be taken with caution until additional independent studies confirm or refute our findings." (PMID 35672347, 2022). "The effect size detected in our study was comparable with that in studies that tested alternative strategies aimed to attenuate insulin resistance in individuals with obesity, such as a plant-based diet, Akkermansia muciniphila, or FMT." (PMID 35562794, 2022). "The increase in the relative abundance of Coprococcus, Blautia, Bacteroides acidifaciens, Bacteroides uniformis, and Akkermansia muciniphila was positively correlated with insulin sensitivity and counter of obesity." (PMID 36229889, 2022). "Comprising one of the most abundant and diverse forms of gut metabolites, bile acids play a key role in blood glucose regulation, insulin sensitivity, obesity, and energy expenditure." (PMID 36699589, 2022). "Analyzing data from a different pediatric cohort, our group previously showed that increased WHR is related to increased VAT and fasting insulin levels in children with obesity and increased hepatic liver fat content." (PMID 36133310, 2022). "Chemerin is an adipokine with a molecular weight of 14 kDa, involved in various physiological and pathophysiological processes, the regulation of adipogenesis, insulin sensitivity, and immune response, and is increased in obesity." (PMID 36499312, 2022). "In the 1960s, researchers have already found out that BCAAs have direct roles on stimulation of insulin secretion and elevated levels of BCAAs are correlated with obesity and serum insulin." (PMID 35855347, 2022). "There are now significant data that insulin dysregulation due to obesity, aging, or metabolic syndrome exacerbates cognitive decline, possibly due to interfering with Aβ degradative processes." (PMID 39483368, 2022). "Our results suggest that exercise can restore the functional response in specific brain regions that aid in insulin’s ability to regulate appetite, even in persons with obesity, in whom this control system is normally impaired." (PMID 36134657, 2022). "Special attention is paid to their signaling and targets related to glucose and insulin homeostasis, lipid metabolism, adiposity and cardiovascular dysfunction in obesity." (PMID 35458168, 2022). "Another study has demonstrated that mice lacking adipocyte P2Y6 receptor were protected from diet-induced obesity and were characterized by improved glucose tolerance and insulin sensitivity." (PMID 36532779, 2022).
Obesity (continued). "In rodents, high fat diet overfeeding rapidly, and prior to obesity being measurable, induces neuronal inflammation resulting in insulin and leptin resistance in ARC neurons and subsequently fibrous proliferation of glial cells (gliosis)." (PMID 35834069, 2022). "One of these studies showed that the use of mirabegron, a β3-agonist, led to improvements in glucose tolerance and insulin sensitivity in humans having obesity." (PMID 34997461, 2022). "- Anti-obesity, insulin sensitizer (↓body weight; ↓eWAT; ↓adipocyte size; ↓serum triglyceride; ↓serum insulin; ↓glucose; ↓HOMA-IR) (0.01%, 0.025% of diet, 8 weeks). - Anti adipogenesis in 3T3-L1 cells (↓C/EBPα, PPARγ, FASN, Ap2) (5, 10 μM for 48 h)." (PMID 35769384, 2022). "In contrast, genetic deletion of the LPS receptor, the toll-like receptor 4 (TLR4), confers to resistance against high caloric diet-induced obesity, improves glucose tolerance and insulin sensitivity, and promotes adipose tissue browning." (PMID 35259160, 2022). "The results provide preliminary support for muscle mass as a predictor of insulin-glucose homeostasis, independently of obesity status." (PMID 36490255, 2022). "Comparable to serum CRP and insulin, higher salivary CRP and insulin OR 4.94 [95%CI: 1.66,14., OR 2.64 [95%CI: 1.09, 6.38], respectively) were predictive of hyperglycemia and obesity (OR 4.53 [95%CI: 2.40,8.50], OR 3.29 [95%CI: 1.82,5.97], respectively)." (PMID 35757631, 2022). "We conclude obesity leads to adipose tissue dysfunction by promoting impaired adipogenesis and adipokine secretion, increased lipolysis over lipogenesis, insulin resistance, immune response, and inflammation." (PMID 36432612, 2022). "In HFD mice, upregulation of ARG1 reduces infiltration of macrophages in adipose tissue and facilitates polarization of macrophages to M2, thus alleviating obesity and improving insulin sensitivity." (PMID 36338341, 2022). "Accordingly, SAT expression and circulating levels of adiponectin are reduced in obesity and other insulin-resistant conditions, showing a strong inverse relationship with insulin action on substrate metabolism and insulin signalling in skeletal muscle." (PMID 35805088, 2022). "The results showed that the HF before and during pregnancy significantly induced obesity and worsen glucose tolerance, insulin sensitivity, and lipid metabolism in the gestational mice." (PMID 36245521, 2022). "Possible causes linking T2DM to increased cancer prevalence are diverse factors such as aberrant endocrine status, obesity, chronic inflammation, hyperglycemia with increased insulin level, and additional sedentary lifestyle factors." (PMID 36013384, 2022). "The initial studies in brain capillaries have brought evidence of the reduced IRs in obesity and hyperinsulinemia as well as increased endothelial binding and insulin transport through the BBB in experimental-induced DM." (PMID 35052794, 2022). "It was observed that patients with T2D and/or obesity, show decreased concentrations of insulin in the cerebrospinal fluid, despite having high insulin levels in plasma." (PMID 35406040, 2022). "In obesity mice, adipose tissue-derived EVs contained less miR-141-3p and impeded insulin response of hepatocytes." (PMID 35770186, 2022). "In obesity, this increase of insulin concentration is abated and the insulin sensitivity decreases, leading to higher blood glucose levels in the individual." (PMID 35844529, 2022). "Obesity and sex seem to play a major role in central insulin-mediated neural BOLD food-cue reactivity." (PMID 35715625, 2022). "Insulin hypersecretion is generally considered as an initial adaptive response to compensate for the reduced insulin sensitivity that often characterises obesity, and it is sustained by the enhancement of both insulin synthesis and secretion in mice." (PMID 35628332, 2022).
Obesity (continued). "The activation of these inflammatory pathways is crucial because the activation of IKKβ/NF-κB influences leptin and insulin metabolism, affecting even the processes of glucose intolerance in obesity." (PMID 35422689, 2022). "This protein stimulates insulin secretion in response to food intake, and it has been proposed as an obesity‐promoting hormone." (PMID 34935299, 2022). "have found that, in people with obesity and insulin resistance, relative abundance (RA) of Firmicutes decreases, whereas compared with insulin sensitive subjects, Bacteroidetes and Proteobacteria RA increase." (PMID 35865314, 2022). "Both obesity and aging impair adipogenesis, the process by which adipocyte progenitors differentiate into functional, insulin-responsive adipocytes." (PMID 36726470, 2022). "Consistent to our results, loss of Ntn1 expression in AT macrophages lead to improved maintenance of glucose homeostasis and insulin sensitivity during obesity." (PMID 36297056, 2022). "The results showed that MLE improved obesity, insulin signaling, abnormal lipid metabolism, liver damage in vivo, and improved lipid accumulation in vitro." (PMID 36014355, 2022). "Lastly, the insulin resistance mechanism is one of the fundamental pathways involved in the pathophsiology of obesity." (PMID 36401211, 2022). "Considering UCP1′s role in controlling blood glucose, insulin sensitivity, mitochondrial density, and fat metabolism, brown adipose tissue is thought to prevent obesity and diabetes." (PMID 36355818, 2022). "Metabolic stresses alter the signaling and actions of insulin in adipocytes during obesity, but the molecular links remain incompletely understood." (PMID 36010657, 2022). "Obesity results in the deregulation of several cell-intrinsic pathways partly due to increased fatty acid influx and ceramide build-up, thus impairing insulin signal transmission." (PMID 35789435, 2022). "Our results represent the potentially considerable effects of maternal overweight or obesity on fetal growth via GDM in the glucose/insulin pathway." (PMID 35268050, 2022). "The novel regulator of macrophage polarization Kruppel-like factor 4 (KLF4) also controls adipogenesis, while IRF3 plays an important role in the regulation of insulin sensitivity, inflammation, and obesity." (PMID 35456006, 2022). "History of parental obesity and T2D is manifested as altered cerebral insulin sensitivity and reduced MOR and CB1R availability." (PMID 34728775, 2022). "This study investigated the relationship between PGG’s insulin mimetic action and its anti-obesity effect by determining the biological activity of PGG at each stage of the adipocyte lifecycle." (PMID 35409415, 2022). "Not all studies to date have looked at confounding factors such as obesity or circulating insulin levels." (PMID 35636492, 2022). "Adolescents have different metabolic characteristics compared to adults due to pubertally-mediated changes in insulin sensitivity, which present in addition to effects of obesity." (PMID 35991189, 2022). "It has been demonstrated that mice without neutrophil elastase have low levels of AT inflammation with improved insulin sensitivity, which suggests that these cells play a role in the regulation of AT inflammation in the early stages of obesity." (PMID 35321537, 2022). "In pathological conditions such as overweight, obesity and T2D, individuals have impaired insulin and post-meal MBF responsiveness." (PMID 35676248, 2022). "Physical exercise promotes several systemic adaptations, including increased insulin sensitivity and improved glucose homeostasis, that reduce obesity and T2DM risks." (PMID 35669687, 2022). "Obesity and sex influenced the central insulin-mediated neural BOLD activity to visual food cues in brain regions implicated in reward and cognitive control." (PMID 35715625, 2022).